INS (insulin)
Diseases named in the same sentence as INS in open-access papers (continued):
Sharing a sentence is not in itself a finding about the gene and the disease.
Insulin resistance (continued). "In T2DM, blood glucose rises because of the inability of the cells to effectively use the insulin that is being produced (insulin resistance), and over time, the production of insulin progressively decreases." (PMID 37775653, 2023). "The lipid metabolism (synthesis and degradation) is an insulin-dependent process and thus is entirely compromised during insulin resistance." (PMID 36810903, 2023). "It has also been observed that decreased miR-22 expression in serum EVs correlates negatively with markers of adipogenesis and insulin sensitivity, such as PPAR at the hepatic level, promoting lower insulin sensitivity and, thus, insulin resistance." (PMID 36830957, 2023). "In both humans and animals, the GTT provides an indication of the relative roles of insulin secretion and insulin resistance in the progression of glucose intolerance." (PMID 36967663, 2023). "Accordingly, to avoid using methods for determining insulin resistance, insulin-free surrogate indices for estimating insulin resistance have been investigated in the general population." (PMID 38068348, 2023). "In response to insulin resistance, the pancreas increases insulin production, which can lead to hyperinsulinemia." (PMID 37868505, 2023). "NZE women had lower HbA1c, lower fasting plasma concentrations of insulin, and lower Homeostatic Model Assessment of Insulin Resistance (HOMA-IR) scores compared to Pacific women." (PMID 36799472, 2023). "We will use fasting insulin and glucose to estimate insulin resistance by calculating Homeostatic Model Assessment-Insulin Resistance (HOMA-IR)." (PMID 37475033, 2023). "During insulin resistance, a great deal of insulin secreted by the body compensates for the glucose metabolism disorder, thereby gradually developing into hyperinsulinemia." (PMID 37830511, 2023). "Due to post-receptor insulin signaling defects, there is insulin resistance and an increase in non-insulin mediated glucose uptake." (PMID 37120562, 2023). "In conclusion, our study unveils LPCAT3 as a novel mediator of reciprocal regulation between phospholipid remodeling and insulin signaling that contributes to the pathogenesis of insulin resistance." (PMID 37088778, 2023). "The homeostasis model assessment for insulin resistance (HOMA-IR) index, the most popular indirect technique, is susceptible to the precision of insulin measurement and has low consistency." (PMID 37273533, 2023). "The reciprocal cause-effect relationship also exists as uric acid is known to impede insulin signalling and induce insulin resistance." (PMID 38274913, 2023). "Insulin resistance (IR), mainly due to dysregulation of insulin signaling pathways, is generally considered to be the crucial pathogenesis of T2D." (PMID 38231654, 2023). "Insulin resistance (IR) is characterized by decreased sensitivity and responsiveness of insulin target organs or tissues to insulin, which impairs the abilities of glucose uptake and utilization, leading to hyperinsulinemia." (PMID 37891647, 2023). "SIRT1 controls insulin secretion by preserving pancreatic β-cells, improves insulin resistance, inflammation, mitochondrial function, controls oxidation of fatty acid and regulates hepatic glucose production." (PMID 37089941, 2023). "The condition of leptin resistance, observed in both obese animals and humans, can also attenuate cellular insulin sensitivity, and, in turn, insulin resistance can impair leptin signaling, thus leading to the frequent co-existence of T2DM and obesity." (PMID 37298571, 2023). "For T2D, central insulin resistance is characterized by a decrease in insulin receptor expression, insulin binding to receptors, and abnormal insulin signaling." (PMID 37833898, 2023). "A decrease in insulin resistance and increased insulin secretion has been reported with vitamin D supplementation." (PMID 37111216, 2023).
Insulin resistance (continued). "It is also an insulin sensitizer, promoting insulin action by improving insulin resistance, and it increases the secretion of anti-inflammatory cytokines." (PMID 37628382, 2023). "To analyze the role of PKN1 activation in response to insulin, we established an experimental model of hyperinsulinemia, mimicking insulin resistance in vitro." (PMID 37242297, 2023). "Insulin resistance and compensatory hyperinsulinism facilitates ovarian androgen excess because insulin acts as a co-gonadotropin at the ovary." (PMID 37076926, 2023). "LNCB has been suggested to disturb reward systems, activate the cephalic phase insulin response, and induce gut microbiota dysbiosis, which can further lead to insulin resistance and the development of type 2 diabetes." (PMID 37085478, 2023). "These bioactive components have the potential to regenerate pancreatic β cells, enhance insulin release, and reverse insulin resistance, all of which are desirable in the control and prevention of several metabolic disease states." (PMID 36902074, 2023). "Our research team previously demonstrated that ~ 7% weight reduction in patients with insulin resistance improves insulin sensitivity by ~ 57%." (PMID 37046323, 2023). "Throughout the literature, patients with Dunnigan disease showed increased fasting glucose, increased HbA1c values, high plasma insulin and higher insulin resistance index (HOMA-IR) than healthy controls." (PMID 36899861, 2023). "This hepatokine represents an important link between obesity and insulin resistance since it is known that Fetuin-A inhibits insulin signaling through the inhibition of IRS-1 phosphorylation in activated tyrosin kinase insulin receptors." (PMID 37998747, 2023). "In the case of insulin resistance, the inhibition of fat breakdown by insulin can be hindered, leading to an increase in circulating FFA levels." (PMID 37836761, 2023). "Given the reciprocal relationship between fatty liver disease and insulin sensitivity, we examined glucose clearance and insulin signaling in FFC-EtOH fed mice to determine the role of insulin resistance in SMAFLD pathogenesis." (PMID 37134024, 2023). "All participants in this group had acanthosis nigricans as a clinical sign of insulin resistance and were being treated with metformin, with three being on a combination of metformin and insulin." (PMID 37897565, 2023). "FFAs in hepatocytes induce alterations in insulin signaling pathways and contribute to insulin resistance." (PMID 37998747, 2023). "PDAC-associated type 3c diabetes is characterized by a decreased secretion of insulin and increased insulin resistance." (PMID 37509329, 2023). "Insulin is known to play a role in adaption to myocardial stress, with insulin resistance contributing to worsening cardiac function." (PMID 38505536, 2023). "The lowest responsiveness (maximal effect of insulin) or sensitivity (insulin concentration required for half the maximum response) to the actions of insulin is called insulin resistance (IR)." (PMID 37241071, 2023). "Inositol, particularly mI and D-chiro-inositol, seems to act as metformin on insulin resistance, thus reducing fasting insulin, homeostasis model assessment (HOMA) index, and body mass index (BMI)." (PMID 36826058, 2023). "Impairment of insulin signaling, which characterizes insulin resistance, will then inhibit myo-Ins conversion into its epimer." (PMID 37047265, 2023). "Elevated insulin levels promote excess fat storage, and weight gain occurs, thus making insulin resistance worse." (PMID 37937009, 2023). "HOMA-IR (Homeostatic Model Assessment of Insulin Resistance) can quantitatively assess how much insulin your pancreas needs to keep your blood sugar levels in check." (PMID 36911663, 2023). "There are many different methods to describe insulin sensitivity, such as the homeostasis model assessment for insulin resistance (HOMA-IR), C-peptide, and the TyG index." (PMID 36852374, 2023).
Insulin resistance (continued). "In a meta-analysis including 11 randomized controlled trials (388 subjects), RSV significantly reduced fasting glucose, insulin, HbA1C and insulin resistance in T2D patients." (PMID 37237968, 2023). "Insulin resistance (IR) is a rather common condition that is often diagnosed on the basis of an arbitrary "increased insulin value" or the presence of symptoms indicative of the Metabolic Syndrome [...]." (PMID 37835038, 2023). "Considering the different effects of amino acids on insulin sensitivity, the composition of amino acids in the body plays an important role in the regulation of insulin resistance." (PMID 37960324, 2023). "The pathophysiology of GDM is not yet fully understood, although it generally involves relatively insufficient insulin secretion with increased peripheral insulin resistance that develops during pregnancy." (PMID 36717953, 2023). "Ectopic lipid storage in insulin-targeted organs, including the liver, promotes insulin resistance and its complications, including non-alcoholic fatty liver disease (NAFLD), which was reported in the literature in up to 83% of FPLD2 cases." (PMID 36899861, 2023). "The serum insulin level was strikingly increased in DM rats but normalized after tirzepatide treatment, suggesting tirzepatide conduced to the amelioration of insulin resistance in diabetic rats." (PMID 37701028, 2023). "T2DM is a chronic condition characterized by decreased insulin sensitivity, known as "insulin resistance," in the liver, muscles, and adipose tissue, accompanied by reduced pancreatic cell secretory activity." (PMID 38111457, 2023). "Lower adiponectin expression and circulating levels are associated with dysfunctional adiposity and precede the deterioration of insulin sensitivity in the prediabetic state, thus predicting the development of insulin resistance and T2DM." (PMID 37371501, 2023). "Exercise increases adiponectin levels that regulate insulin sensitivity, decreases insulin resistance, and activates AMPK to regulate glucose and lipid metabolism." (PMID 37964253, 2023). "Chemerin also stimulates insulin-mediated glucose uptake and improves insulin action in 3T3-L1 adipocyte to treat obesity and insulin resistance." (PMID 37033655, 2023). "As obesity progresses, adipocytes develop hypertrophy, resulting in severe impairment of insulin signaling, which is known to contribute to insulin resistance." (PMID 36771210, 2023). "More than 90% of DM cases are type 2 (T2DM), which is mainly caused by a combination of two factors: the failure of insulin secretion by the pancreatic β-cells and the inability of insulin-sensitive tissues to respond to insulin (insulin resistance)." (PMID 37606429, 2023). "Insulin resistance is referred to as a blunted response of insulin tissue targets to this hormone leading to impaired glycaemic control, dyslipidemia along with an increased risk of developing cardiovascular disease and certain types of cancer." (PMID 36979141, 2023). "Early in disease progression, oral hypoglycemic agents (OHAs) effectively lower insulin resistance or improve insulin secretion." (PMID 37264625, 2023). "On the other hand, elevated triglyceride levels can increase insulin resistance by promoting the accumulation of fatty acids within cells, inducing inflammation, and disrupting insulin signaling pathways." (PMID 38004101, 2023). "Insulin resistance also facilitates the high blood pressure that occurs in Met-S by losing the vasodilator effect of insulin and the vasoconstriction produced by free fatty acids that produce reactive species and eliminate nitric oxide." (PMID 36678129, 2023). "In the liver, increased DAG content was associated with the activation of PKCε isoform both in experimental models of hepatic insulin resistance and in humans with hepatic steatosis and insulin resistance, leading to impaired proximal insulin signaling." (PMID 37232722, 2023).
Insulin resistance (continued). "The oral administration of oleuropein improved glucose tolerance and reduced insulin content in high fat diet induced insulin resistance in rats." (PMID 36647430, 2023). "The balance between insulin/insulin resistance induced cell stress and the cytoprotective response determines detrimental effects of hyperinsulinemia and insulin resistance." (PMID 37854186, 2023). "Previous studies using selective PPARγ activators, including SR1664, suggested that these agents are effective in improving insulin resistance through their insulin-sensitizing effects." (PMID 37886997, 2023). "Specifically, total lipids, glucose, insulin, homeostatic model assessment for insulin resistance (HOMA-IR), glycated hemoglobin (HbA1c), thyroid stimulating hormone [TSH], fT3, and fT4 were assessed." (PMID 37761412, 2023). "The accumulation of ectopic fat and its derivatives in organs and tissues impairs insulin action and signaling leading to a state of insulin resistance." (PMID 38140310, 2023). "Insulin resistance was improved by reducing HbA1c, plasma insulin, and HOMA-IR levels in the HMC group." (PMID 37432173, 2023). "PHE has also been found to alter insulin secretion and increase blood glucose levels in animal models, potentially contributing to insulin resistance." (PMID 37334286, 2023). "Insulin resistance is defined as an impairment of insulin action in its target tissues, including mainly the liver, adipose tissue and muscle." (PMID 37237860, 2023). "For example, the most used in T2DM management are insulin secretagogues, drugs that reduce insulin resistance, and carbohydrate digestive enzyme inhibitors (AGIs)." (PMID 36062030, 2023). "Indexes of insulin resistance, sensitivity and β-cell function were calculated based on glucose and insulin values from 2-hour oral glucose tolerance tests (OGTT) and fasting C-peptide." (PMID 37568149, 2023). "As CMS progresses, the pancreas struggles to produce sufficient insulin to overcome insulin resistance, leading to impaired glucose tolerance and eventually T2DM." (PMID 37868505, 2023). "Although apelin increases insulin resistance and appears to inhibit pancreatic insulin secretion, insulin sensitivity in animal models improved following apelin therapy." (PMID 36779088, 2023). "Hyperuricemia in obesity and insulin resistance is thought to result from decreased insulin‐dependent renal tubular uric acid excretion and/or increased fructose‐dependent uric acid production." (PMID 36415168, 2023). "It is also known that OW or OB subjects often have higher values of plasma insulin and insulin resistance (expressed as Homeostasis Model Assessment, HOMA-index) than normal-weight peers, even in pediatric age." (PMID 36984767, 2023). "Overnutrition or high-fat diet-induced obesity leads to brain insulin resistance and impairs systemic insulin sensitivity and glucose homeostasis in both humans and mice." (PMID 37960324, 2023). "On the other hand, the noradrenergic phenotype mainly acts by increasing insulin resistance and, therefore, insulin-sensitizing antidiabetic agents can find a greater application." (PMID 36982228, 2023). "Insulin resistance in the brain is a condition in which brain cells become less responsive to the effects of insulin, leading to a decline in cognitive function and an increased risk of neurodegeneration." (PMID 38133370, 2023). "Insulin resistance and adiposity stimulate insulin secretion, which, in turn, activates ovarian androgen production." (PMID 36484476, 2023). "T2D, instead, is characterized by peripheral insulin resistance (IR) compensated for by the production of more insulin culminating in overt hyperglycemia." (PMID 37396181, 2023). "A HOMA-IR result above 2.9 suggests advanced insulin resistance, indicating severe resistance to insulin's actions and a higher likelihood of developing metabolic disorders such as type 2 diabetes." (PMID 38024834, 2023).
Insulin resistance (continued). "Inflammatory cytokines, such as tumor necrosis factor-alpha (TNF-α) and interleukin-6 (IL-6), can potentially hinder insulin signaling in renal cells, resulting in insulin resistance." (PMID 37868469, 2023). "Chronic hyperglycemia, insulin resistance, or insulin deficit result in excess generation of FFA from adipose tissue to the heart and increase cardiac lipase activity." (PMID 35841183, 2023). "Insulin resistance, a hallmark of CKD, arises when cells exhibit diminished responsiveness to insulin’s regulatory signals." (PMID 38276262, 2023). "Insulin resistance occurs when β-cells cannot produce enough insulin due to impaired insulin sensitivity." (PMID 37444337, 2023). "Our study found that newly diagnosed type 2 diabetes patients received GLP-1RA treatment, their insulin secretion index increased significantly, and the insulin resistance index decreased compared with the control group." (PMID 37255814, 2023). "In T2DM, the effects of insulin are counteracted by factors that induce a state of insulin resistance." (PMID 36675238, 2023). "Primary outcome: Fasting values for glucose and insulin, and markers of insulin resistance at baseline and after the 10-week intervention." (PMID 36760521, 2023). "Insulin resistance: Insulin resistance is characterized by the reduced ability of insulin to activate insulin signaling and glucose uptake." (PMID 36768567, 2023). "Insulin resistance and lipid metabolic disorders have been linked to PTP1B, the enzyme that negatively regulates the insulin and leptin signaling pathways." (PMID 37408757, 2023). "We found that the glucose infusion rate (GIR) necessary to maintain euglycemia during the insulin clamp was reduced, consistent with the development of insulin resistance." (PMID 38060313, 2023). "The insulin clamp test, which is the gold standard for identifying insulin resistance, is difficult to perform both in clinical and primary care settings." (PMID 37370012, 2023). "Muscle insulin resistance is considered an essential component of whole-body insulin resistance since skeletal muscle is responsible for about 60–70% of insulin-stimulated glucose disposal in the entire body." (PMID 37876013, 2023). "The proline plasma levels have been shown to be increased in patients with T2DM, obesity, and insulin resistance; such persistent alterations lead ultimately to impaired insulin secretion, systemic glucose homeostasis disruption, and other dysfunctions." (PMID 37736814, 2023). "In a randomized controlled trial, blueberry intake improved insulin sensitivity by approximately 22% in obese individuals with insulin resistance." (PMID 37371912, 2023). "Because of the fact that C-peptide is produced in equimolar amounts to endogenous insulin, its elevated levels are characteristic of insulin resistance and the metabolic syndrome phenotype, which are associated with hyperinsulinemia." (PMID 37180128, 2023). "Other studies have used fructose to represent added sugar and have found that greater concentrations of fructose (15% to ≥ 25% of total calories) promote insulin resistance, increase fasting plasma glucose concentrations, and impair insulin sensitivity." (PMID 37339144, 2023). "For glucagon, insulin resistance was associated with a shift in estimated IC50 of insulin and was similar to the fasting insulin for insulin-sensitive individuals with a GIR20–60min ≥ 10.8 mg/kg-LBM/min of 5.1 μU/mL." (PMID 36752854, 2023). "Failure of GLUT4 to undergo insulin-stimulated translocation to the PM represents a major manifestation of insulin resistance in type 2 diabetes." (PMID 37791639, 2023). "It seems that the mechanism described in polycystic ovary syndrome associated with excess visceral fat and reduced insulin sensitivity leading to insulin resistance and high blood insulin concentrations comes to the fore." (PMID 36986218, 2023).